EXOSC1 (exosome component 1)
Description:
Non-catalytic component of the RNA exosome complex which has 3'->5' exoribonuclease activity and participates in a multitude of cellular RNA processing and degradation events. In the nucleus, the RNA exosome complex is involved in proper maturation of stable RNA species such as rRNA, snRNA and snoRNA, in the elimination of RNA processing by-products and non-coding 'pervasive' transcripts, such as antisense RNA species and promoter-upstream transcripts (PROMPTs), and of mRNAs with processing defects, thereby limiting or excluding their export to the cytoplasm. The RNA exosome may be involved in Ig class switch recombination (CSR) and/or Ig variable region somatic hypermutation (SHM) by targeting AICDA deamination activity to transcribed dsDNA substrates. In the cytoplasm, the RNA exosome complex is involved in general mRNA turnover and specifically degrades inherently unstable mRNAs containing AU-rich elements (AREs) within their 3' untranslated regions, and in RNA surveillance pathways, preventing translation of aberrant mRNAs. It seems to be involved in degradation of histone mRNA. The catalytic inactive RNA exosome core complex of 9 subunits (Exo-9) is proposed to play a pivotal role in the binding and presentation of RNA for ribonucleolysis, and to serve as a scaffold for the association with catalytic subunits and accessory proteins or complexes. EXOSC1 as peripheral part of the Exo-9 complex stabilizes the hexameric ring of RNase PH-domain subunits through contacts with EXOSC6 and EXOSC8.
Synonyms: CSL4; CGI-108; hCsl4p; Csl4p; Ski4p; SKI4; p13; PCH1F
Tractability: Small molecule: a structure with a bound ligand is known. PROTAC: ubiquitination databases record sites on it; its protein half-life has been measured.
Gene: Protein-coding gene on chromosome 10 (97,428,014 to 97,446,085, reverse strand). Ensembl gene ENSG00000171311.
Subcellular location: Nucleus, nucleolus; Nucleus; Cytoplasm
Subcellular location (Human Protein Atlas): Nuclear bodies; Nucleoplasm
Pathways (Reactome):
Metabolism of RNA: Butyrate Response Factor 1 (BRF1) binds and destabilizes mRNA; KSRP (KHSRP) binds and destabilizes mRNA; Major pathway of rRNA processing in the nucleolus and cytosol; Nuclear RNA decay; Tristetraprolin (TTP, ZFP36) binds and destabilizes mRNA; mRNA decay by 3' to 5' exoribonuclease
Cellular responses to stimuli: ATF4 activates genes in response to endoplasmic reticulum stress
Gene Ontology:
Molecular function: protein binding; RNA exonuclease activity; RNA binding; nucleic acid binding
Biological process: RNA catabolic process; RNA processing
Cellular component: cytosol; exosome (RNase complex); nucleolus; nucleus; cytoplasm; cytoplasmic exosome (RNase complex); nuclear exosome (RNase complex); nucleolar exosome (RNase complex); nucleoplasm
Genetic constraint (gnomAD): Loss-of-function variants: 26 observed, 30.08 expected, observed/expected ratio (o/e) 0.86, 90% interval 0.63 to 1.2. The upper end of that interval is the gene's LOEUF score, 1.2, which puts it in group 5 of 6, group 1 being the genes least tolerant of losing a copy. Missense variants: 220 observed, 254.11 expected, observed/expected ratio (o/e) 0.87, 90% interval 0.77 to 0.97. Synonymous variants: 81 observed, 94.62 expected, observed/expected ratio (o/e) 0.86, 90% interval 0.71 to 1.03.
Homologues: Orthologues: chimpanzee EXOSC1 (100% identical), dog EXOSC1 (97% identical), guinea pig EXOSC1 (97% identical), mouse Exosc1 (96% identical), rat Exosc1 (96% identical), pig EXOSC1 (91% identical), zebrafish exosc1 (79% identical), tropical clawed frog exosc1 (78% identical), Drosophila melanogaster Csl4 (47% identical), Caenorhabditis elegans exos-1 (33% identical).
Diseases named in the same sentence as EXOSC1 in open-access papers:
EXOSC1 is named in the same sentence as 11 diseases in open-access papers, as found by Europe PMC text mining. Sharing a sentence is not in itself a finding about the gene and the disease. The quoted sentences say what the papers report.
Autoimmunity (1 paper, 2016). The occurrence of an immune reaction against the organism's own cells or tissues. "The one significant DMR after adjustment for cell type from the ACPA-positive RA discordant twins associates with the EXOSC1 gene, which codes for a core component of the exosome involved in the processing, controlling, and degrading of RNA and in cytokine regulation and autoimmunity." (PMID 27876072, 2016).
colon adenocarcinoma (1 paper, 2022). "Various potential biomarkers for colon adenocarcinoma initiation and progression and drug targets were identified and discussed, including seven novel markers: ACSL4, ANK2, AMER3, EXOSC1, EXOSC6, GCLM, and TFRC." (PMID 35842572, 2022).
inflammatory bowel disease (1 paper, 2016). A spectrum of small and large bowel inflammatory diseases of unknown etiology. "Also, bioinformatic analysis targeting inflammatory bowel disease (IBD), among other diseases, revealed that EXOSC1 was one of the top upregulated genes associated with the disease." (PMID 27876072, 2016).
melanoma (1 paper, 2022). A malignant, usually aggressive tumor composed of atypical, neoplastic melanocytes. "Array CGH and PPI mapping integrating study has proved that EXOSC1/3/8 were predicted to be the functional interaction factors in the network of the 6q23.3 locus in melanoma." (PMID 36293016, 2022).
stomach cancer (1 paper, 2024). "The expression of EIF4E, EXOSC1, IARS1, IGFBP1, and SPCS1 was found to be upregulated in stomach cancer cell lines, while TSPYL2 and TUBB2A showed downregulated expression." (PMID 38700505, 2024).
cancer (2 papers, 2021). A tumor composed of atypical neoplastic, often pleomorphic cells that invade other tissues. "Considering the central roles of mutation in the process of cancers, we evaluated the potential clinical significance of EXOSC1 in KIRC using KM analyses." (PMID 34159897, 2021). "Due to the capability of EXOSC1 to cleave DNA and promote mutations, EXOSC1 might enhance mutations and consequently provide genetic fuel for cancer development, metastasis, and even therapy resistance." (PMID 34159897, 2021). "An inspection of CRISPR screening of 1054 cancer cell lines using DepMap showed that EXOSC1–10 and DIS3 (EXOSC11) are essential in most cancer cell lines." (PMID 34948199, 2021). "Consistent with the capability of EXOSC1 to promote DNA damage and mutations, KIRC patients with high EXOSC1 showed a poor prognosis, and EXOSC1 also sensitized cancer cells to the PARP inhibitor." (PMID 34159897, 2021). "Notably, KIRC patients with high EXOSC1 showed a poor prognosis, and EXOSC1 sensitized human cancer cells to poly(ADP-ribose) polymerase inhibitors." (PMID 34159897, 2021). "In this study, we show that EXOSC1 acts as an ESM and sensitizes cancer cells to PARPi in KIRC." (PMID 34159897, 2021). "Considering that EXOSC1 increases DNA damage, we speculated that EXOSC1 potentially sensitizes KIRC cells to the inhibitors of poly(ADP-ribose) polymerase (PARP), which treats cancers via blocking DNA repair." (PMID 34159897, 2021).
tumor (1 paper, 2021). "Additionally, a subcutaneous xenograft tumor model was used to determine whether EXOSC1 enhances DNA mutations in vivo." (PMID 34159897, 2021).
EXOSC1 also shares sentences with these, for which no sentence is quoted: Alzheimer disease (1 paper); genetic disorder (1); infection (1); oral cancer (1).